RNU6-737P (RNA, U6 small nuclear 737, pseudogene)
Gene: Small nuclear RNA gene on chromosome 18 (57,284,602 to 57,284,708, reverse strand). Ensembl gene ENSG00000202240.
Homologues: Orthologues: chimpanzee U6 (98% identical), macaque U6 (97% identical), dog U6 (81% identical). Paralogues in human: RNU6-12P (93% identical), RNU6-13P (93% identical), RNU6-32P (93% identical), RNU6-1 (93% identical), RNU6-16P (93% identical), RNU6-17P (93% identical), RNU6-18P (93% identical), RNU6-2 (93% identical), RNU6-26P (93% identical), RNU6-31P (93% identical), RNU6-3P (93% identical), RNU6-45P (93% identical), and 1288 more.